ABCG2 (ATP binding cassette subfamily G member 2 (JR blood group))
Diseases named in the same sentence as ABCG2 in open-access papers (continued):
Sharing a sentence is not in itself a finding about the gene and the disease.
cancer (continued). "Other studies indicate that the regulatory functions of individual C19MC miRNAs in cancer are related to silencing the expression of factors and signaling pathways related to adhesion, migration, differentiation, growth and angiogenesis (Rap1b, ABCG2, DAPK2, ephrins-EphB2 and EphB4, CXCR4)." (PMID 36430313, 2022). "Interestingly, an increasing number of FDA-approved tyrosine kinase inhibitors (TKIs), including imatinib and gefitinib, reported to downregulate or inactivate ABCG2 and, therefore, may serve as candidates to reverse cancer stem cell chemoresistance." (PMID 34884848, 2021). "It has also been reported that the activity of CUDC-907 in ABCG2-overexpressing cancer cells can be restored by inhibiting the function of the ATP-binding cassette drug transporter, ABCG2, which is one of the most common mechanisms for multidrug resistance in cancers." (PMID 33663586, 2021). "Nowadays, the largest challenge for cancer drug treatment is MDR initiated by the elevation of the ATP-binding cassette (ABC) efflux transporters, including P-glycoprotein (P-gp/ABCB1), multidrug resistance-associated protein 1 (MRP1/ABCC1) and breast cancer resistance protein (BCRP/ABCG2)." (PMID 34026649, 2021). "Therefore, we investigated whether the activity of citarinostat is also affected by the drug efflux function of ABCB1 and ABCG2 in human cancer cell lines in a similar manner as ricolinostat." (PMID 33807514, 2021). "However, ABCG2 is overexpressed in cancer cells and plays a crucial role in the development of MDR." (PMID 34830383, 2021). "Therefore, the aim of this study was to investigate the impact of ABCB1 and ABCG2, two of the most common mechanisms of resistance to conventional and molecularly targeted anticancer drugs, on the efficacy of citarinostat in human cancer cell lines." (PMID 33807514, 2021). "Interestingly, it has been suggested that BCRP/ABCG2 may affect the important role of cancer stem cells in drug resistance." (PMID 33801360, 2021). "Furthermore, triclabendazole and its metabolites can inhibit ABCG2/BCRP, an ATP-binding cassette transporter that extrudes compounds from cells in the intestine, liver, kidney, and gland, affecting pharmacokinetics of anti-cancer drugs." (PMID 34305590, 2021). "Therefore, CBZ could re-sensitize cancer cells that are resistant to ABCG2 substrate drugs including topotecan (TPT)." (PMID 33829017, 2021). "Therefore, it is conceivable that Cisplatin could be secreted from cancer cells via ABC transporters such as ABCG2 efflux pump and/or exosomes." (PMID 33562088, 2021). "However, we found that citarinostat had a significantly reduced effect on HDAC6 in ABCB1-overexpressing KB-V-1 and ABCG2-overexpressing S1-M1-80 cancer cells as compared to the respective parental KB-3-1 and S1 cancer cells." (PMID 33807514, 2021). "However, the mutations in ABCB1, ABCA1, ABCC1 and ABCG2 did not affect overall cancer survival rates as determined by log-rank tests (all P-values < 0.05)." (PMID 34541464, 2020). "Therefore, instead of synthesizing novel modulators, an alternative approach is to explore the possibility of repurposing FDA-approved tyrosine kinase inhibitors (TKIs) to resensitize ABCB1- or ABCG2-overexpressing multidrug-resistant cancer cells to chemotherapeutic agents." (PMID 32466597, 2020). "Furthermore, we found that the drug transport mediated by ABCB1 and ABCG2 was inhibited by sitravatinib in a concentration-dependent manner but the protein expression of ABCB1 and ABCG2 was not significantly altered by sitravatinib in multidrug-resistant cancer cells overexpressing ABCB1 or ABCG2." (PMID 31941029, 2020). "Therefore, the data indicate that the paclitaxel → AR/AhR → ABCG2 axis might form a positive feedback regulatory loop for cancer to develop chemoresistance." (PMID 30986993, 2019).
cancer (continued). "Based on these observations, the modest increase in PpIX‐FI in MCF10A cells and the cell‐to‐cell variability in MCF7 and MDA‐MB‐231 cells observed by flow cytometry may be, at least in part, attributed to the increased expression of ABCG2 in these cancer cell lines." (PMID 31385432, 2019). "Similarly, while topotecan induced substantial apoptosis of S1 cancer cells, from 4% basal level to approximately 35% of total apoptosis, topotecan had minimal effect on ABCG2-overexpressing S1-M1-80 cancer cells, likely a result of ABCG2-mediated efflux of topotecan." (PMID 31905792, 2019). "Therefore, the different sized Ru@MSNs could overcome MDR by inhibiting ABCB1 and ABCG2, and consequently enhancing DNA damage mediated cancer cell apoptosis." (PMID 29334793, 2018). "The overexpression of ABCG2 is observed in certain drug-resistant cell lines and tumors, providing a special multidrug-resistant phenotype in these cancer cells, which indicates its possible importance in the multidrug-resistant phenotype of various cancer cells." (PMID 30231526, 2018). "In vitro and in vivo data suggests that dacomitinib may be a great candidate of ABCG2 inhibitors, which advocates further investigation of combination chemotherapy of dacomitinib with conventional anticancer drugs in the cancer patients with ABCG2 overexpression." (PMID 29458405, 2018). "Furthermore, ABCB1 and ABCG2 can co-exist on the surface of many multidrug resistant cancer cells." (PMID 30544754, 2018). "The adenosine triphosphate–binding cassette protein ABCG2 (breast cancer resistance protein [BCRP], mitoxantrone resistance [MXR]) causes multidrug resistance in cancer cells and may have an important function in physiological protection of various tissues against toxic agents." (PMID 30231526, 2018). "In addition, ABCG2 may also be responsible for cancer multidrug resistance, as its overexpression allows tumor cells to remove chemotherapeutic agents." (PMID 29749379, 2018). "In addition to its usefulness as a CSC marker, ABCG2 may be directly involved in cancer-related pathways and functions." (PMID 30002682, 2018). "Thus, cariprazine significantly and selectively modulates MDR in ABCG2 overexpressing cancer cells." (PMID 30181510, 2018). "Notably, HMR1031 strongly suppressed LPS-induced ABCG2 expression in the cancer cell population." (PMID 28969049, 2017). "Nestin expression in cancer cells was immunohistochemically studied in 90 patients with completely resected stage II and stage IIIA NSCLC treated with AC and its association with clinicopathologic parameters, including ABCG2, E-cadherin, and vimentin expression, was evaluated." (PMID 28358810, 2017). "Hence addition of a YAP inhibitor to an ABCG2 substrate like doxorubicin is highly likely to cause a synergetic rather than an additive effect on cancer cell viability." (PMID 27911857, 2017). "It is important to mention that the mechanism by which elevated concentrations of VP + SF when used in combination decrease the viability of highly resistant cancer cells may be unrelated to their ability to downregulate the expression of MDR1 or ABCG2, respectively." (PMID 29201061, 2017). "Additionally, other ABC transporters such as ABCC1/MRP1 and ABCG2 are also overexpressed in cancer cells and could be targeted by plant products." (PMID 28626426, 2017). "However, ABCG2+ and ABCG2—cancer cells are similarly tumorigenic." (PMID 27189061, 2016). "Thus, we hypothesized that combination of a conventional cancer drug with the ability to target ABCG2 would be a better approach to treat MM patients and may improve drug-sensitivity." (PMID 26314844, 2015). "Furthermore, ABCG2 inhibitors enable the regulation of chemoresistance pumps and decrease cancer cell survival and are promising due to their minimal adverse effects to cancer patients." (PMID 26517090, 2015).
cancer (continued). "In addition, ABCG2 is overexpressed in several cell lines selected in the presence of anticancer drugs and functions as a key player in the multidrug-resistance phenotype of cancer cells." (PMID 26536031, 2015). "Importantly, ABCG2 has been reported to be a predictor of shorter survival in cancer patients, which implied that inhibiting ABCG2 might contribute to increased response and prolonged survival rates." (PMID 25436978, 2014). "Hence, our results suggest that using ABCG2 inhibitors to treat MDR cancers may promote the generation of tolerogenic DCs and expansion of Treg cells, thereby helping cancer growth and metastasis." (PMID 25111504, 2014). "In summary, this study showed that afatinib could reverse the drug resistance and enhance the cytotoxicity of conventional anticancer drugs in ABCG2-overexpressing cancer cells by a dual inhibition of ABCG2: inhibiting the drug transport function and downregulating the expression of ABCG2." (PMID 25436978, 2014). "Moreover, in cancer patients with ongoing bacterial infections, the effect of ABCG2 inhibitor can be particularly detrimental, as the combination of ABCG2 inhibitor and bacterial LPS can exacerbate the immunosuppressive state, worsening both the infection and the cancer." (PMID 25111504, 2014). "This may be one of the reasons for the failure of MDR cancer therapy by ABCG2 inhibition." (PMID 25111504, 2014). "Therefore, co-treatment with other anti-cancer drugs, which were also defined as BCRP/ABCG2 substrate, may be an alternative way to enhance the anti-tumor efficacy of sorafenib in HCC cells." (PMID 24391798, 2013). "However, we did not observe any increases in ALDH activity or ABCG2 expression, which are associated with cancer stem cell function." (PMID 24126540, 2013). "Therefore, ABCG2/BCRP as well as MDR1/ABCB1 plays a significant role in drug resistance, and inhibitors for ABCG2/BCRP may enhance the outcome of cancer chemotherapy." (PMID 22355323, 2012). "Since intrinsic resistance was also observed in BCRP/ABCG2-negative cancer cells, the BCRP/ABCG2-mediated drug efflux may not be the only mechanism contributing to insensitivity of wtEGFR-expressing cancer cells to gefitinib, and other mechanisms await to be explored." (PMID 21731744, 2011). "In addition, we may also hypothesize that the CD133+ subset encompasses a smaller CD133+\ABCG2+\SP+ population, which could be resistant to drugs, possesses stem features and may effectively drives cancer progression." (PMID 18941626, 2008). "Drug efflux ABC transporters, such as P-gp, multidrug resistance protein-1 (MRP-1), and breast cancer resistant protein (BCRP, MXR, ABCG2), play a crucial role in various cancers due to their distinct structural and functional characteristics." (PMID 40370595, 2025). "Among them, ABCG2, also known as the breast cancer resistance protein (BCRP), has garnered significant attention due to its role in multidrug resistance (MDR) in cancer therapy." (PMID 41471102, 2025). "Activation of the PI3K/AKT pathway contributes to multidrug resistance (via ABCG2), alters the drug metabolism (via CYP3A4), and enhances cell survival (via MCL1), all of which play key roles in cancer cell resistance to chemotherapy drugs like irinotecan." (PMID 39931465, 2025). "Fumitremorgin C is biosynthesized by A. fumigatus and exerts a potent and selective inhibition of the breast cancer resistance protein (BCRP/ABCG2), an ABC transporter that contributes to multidrug resistance in several types of cancer cells." (PMID 41515980, 2025). "Multidrug resistance (MDR) in cancer therapy, frequently driven by overexpression of ATP-binding cassette (ABC) transporters—particularly ABCG2—continues to undermine the efficacy of chemotherapeutic regimens." (PMID 40584625, 2025).
cancer (continued). "In the ABC transporters module, we observed significant upregulation of multidrug efflux pumps that have previously been reported to be upregulated by GH in other cancers: ABCB5 and ABCB1 in both sexes and ABCG2 in males only." (PMID 40806252, 2025). "TGF-β can activate the AKT pathway, leading to increased expression of cancer stem cell markers (SOX2, ABCG2) and cisplatin resistance." (PMID 40486962, 2025). "The ABCG2, CYP3A4, MCL1, and MLH1 genes are overexpressed in various cancers and are involved in chemoresistance to multiple drugs." (PMID 39931465, 2025). "Three ABC transporters, ABCB1 (P-glycoprotein, P-gp), ABCC1 (multidrug resistance protein 1, MRP1), and ABCG2 (breast cancer resistance protein, BCRP), are key players in multidrug resistance (MDR) phenomena in cancer and microbial infectious diseases." (PMID 40165990, 2025). "ATP-binding cassette (ABC) transporters, particularly ABCG2, play a pivotal role in MDR development by actively expelling chemotherapeutic agents from cancer cells." (PMID 40508176, 2025). "The use of ABCG2 inhibitors and ABCB1 inhibitors, respectively, on ASPC-1 and H2170 cells with high ABCG2 expression and HCT15 cells with high ABCB1 expression can enhance the sensitivity of cancer cells to DXd/SN-38." (PMID 40181988, 2025). "ABCG2, a key transporter involved in MDR, expels chemotherapeutic drugs from cancer cells, thereby diminishing their effectiveness." (PMID 40584625, 2025). "Cells exhibiting high expression of BCAN, GFAP, and EGFR were categorized as cancer cells, while endothelial cells displayed elevated levels of FLT1, CLDN5, and ABCG2." (PMID 41041071, 2025). "Previous studies have shown that BLU-258 at non-toxic concentrations can impair the function of the ATP-binding transporters (ABC) ABCB1 and ABCG2 in vitro and restore chemosensitivity in multidrug-resistant cancer cells overexpressing ABCB1 and ABCG2." (PMID 40076604, 2025). "Cancer stem cell-related markers, CD44, ABCG2, BMI1, and KRT19, expression in subclusters from trajectory, indicated enhanced self-renewal capacity in SRGN-high malignant cells." (PMID 40384866, 2025). "One of the most clinically-relevant is breast cancer resistance protein (BCRP, ABCG2), which confers MDR to several types of human cancers." (PMID 40802735, 2025). "A series of vitro experiments revealed that SRGN expression upregulated ABCG2, BMI1, and Nanog, enhancing the sphere-forming ability of HCC cells and increasing the population of cells with cancer stem cell-like characteristics." (PMID 40384866, 2025). "By downregulating ABCG2 expression, GNP-DSH-WFA enhances the sensitivity of cancer cells to chemotherapeutic agents, thereby improving treatment efficacy." (PMID 40448105, 2025). "ABCG2 is pivotal for physiological detoxification across barrier tissues, but its ectopic expression levels also mediates MDR phenomena in cancer." (PMID 40165990, 2025). "The ABCB1/ABCG2 efflux system at the BBB poses a significant problem for successful drug delivery to the brain, as it hinders the uptake of anti-cancer drugs into the brain and severely limits their efficacy in treating primary and metastatic brain tumors." (PMID 41574208, 2025). "In all MDR cancer cell lines tested, incubation of KSQ‐4279 had few effects on ABCB1/ABCG2/ABCC1 expression both in mRNA level and protein level, even given the treated concentration of KSQ‐4279 higher to 50 μM or the incubated time longer to 72 h." (PMID 41328326, 2025). "To investigate the interaction modes and binding affinities of GC-3,5-diGA and 1,2,4,6-GA-glc with shared targets involved in cancer and oxidative stress, we conducted systematic molecular docking analyses on four target proteins: FGF2, TERT, MMP9, and ABCG2." (PMID 40363725, 2025). "The PI3K/AKT signaling pathway is a common molecular route that links the ABCG2, CYP3A4, and MCL1 genes, particularly in the contexts of cancer and drug resistance." (PMID 39931465, 2025).
cancer (continued). "Well-characterized members of this transporter family include P-glycoprotein (P-gp, also known as MDR-1 or ABCB-1), MRP-1 or ABCC-1, and BCRP or ABCG2, all of which are commonly overexpressed in drug-resistant cancer cells." (PMID 40725123, 2025). "The differential expression of ABCG2 and ALDH1 markers between these cell lines highlights the heterogeneity and complexity of cancer." (PMID 38787133, 2024). "We now show that ABCG2 regulates SLC1A5-mediated glutamine transport, accompanied by rewiring of cancer cell metabolism, enhanced autophagy, and increased tumor cell survival under stress conditions." (PMID 38641063, 2024). "The primary challenge of MDR becoming a treatment for HCC lies in the overexpression of the ATP-binding cassette (ABC) transporter family in cancer cells, including ABCG1, ABCC1, and ABCG2." (PMID 38735927, 2024). "Multidrug resistance mediated by the breast cancer resistance protein (BCRP, ABCG2) is challenging in cancer therapy." (PMID 37727134, 2024). "Here, we primarily investigate the impact of ABCG2 gene expression on the NSCLC development, course of cancer disease, and patient prognosis using data collected in databases." (PMID 39457707, 2024). "ABCG2, which is one of the members of ABC superfamily G, confers therapy resistance to cancer cells by promoting drug efflux." (PMID 38726001, 2024). "ABCB1, ABCC1, and ABCG2, are key members of the ATP-binding cassette (ABC) transporter family, which are crucial for multidrug resistance in cancer cells." (PMID 39574476, 2024). "Additionally, it has been shown that the overexpression of ABCG2 in cancer cells enhances the process of autophagy induced by non-substrate stressors (such as radiation or nutrient starvation), contributing to increased cell survival and promoting cancer progression." (PMID 39457707, 2024). "We investigated the effect of polystyrene nanoparticles (PSNPs) on cancer cell stemness using flow cytometric analysis of CD24, CD44, ABCG2, ALDH1 and their combinations." (PMID 38787133, 2024). "In this study, we further observed the downregulation of NRF2 target genes, namely ABCG2, GCLM, and SLC1A1, which are involved in ferroptosis regulation, only in HSC2 cancer cells." (PMID 39857335, 2024). "Among those subfamilies, the three major types involved in cancer drug resistance are ABCB1, ABCC1, and ABCG2, which represent MDR1, MRP1, and BCRP proteins, respectively." (PMID 38326737, 2024). "Further, miR-520h was found to modulate ABCG2 expression in PANC-1 cells and contribute to cancer cell migration and invasion." (PMID 39114355, 2024). "Understanding the complex role of ABCB1, ABCC1, and ABCG2 in acquired resistance is critical for improving strategies to overcome MDR, increasing treatment efficacy, and ultimately improving outcomes for cancer patients." (PMID 38893104, 2024). "Subsequently, the expression of both HIF-1α and ABCG2 was decreased by miR-519c, resulting in the decrease of GLUT1 expression as well as cancer cell metabolism under hypoxia." (PMID 39479443, 2024). "Background/Objectives: ATP-binding cassette subfamily G member 2 [ABCG2/breast cancer resistance protein (BCRP)] contributes to mechanisms of multidrug resistance (MDR) and is a marker of side population (SP) cells in human cancers." (PMID 39457707, 2024). "ABCG2, a member of the ATP-Binding Cassette (ABC) transporter superfamily, is renowned for its role in diminishing the chemosensitivity of cancer cells to conventional cytotoxic anticancer drugs." (PMID 38791198, 2024). "CD147 is a hub Ag that binds to other proteins (Intergrin, Hyaluronan, CD44, P‐gp/ABCB1, ABCG2, MCT‐1/4, CypA/B, and Gasdermin D) to drive the malignancy of cancer cells." (PMID 38469549, 2024). "CSCs efficiently express ABC transporter proteins, such as MDR1/ABCB1, MRP1/ABCC1, and ABCG2, that belong to multidrug resistance proteins and ensure cancer cells’ resistance to anticancer therapy." (PMID 37626893, 2023).